CD274 (CD274 molecule)
Diseases named in the same sentence as CD274 in open-access papers (continued):
Sharing a sentence is not in itself a finding about the gene and the disease.
tumor (28,820 papers, 2005 to 2026). "The rs7603052 polymorphism in PDCD1 and rs17718883 in CD274 were significantly associated (p = 0.033 and p = 0.043 respectively) with PD-L1 expression in tumor-infiltrating immune cells (TIICs)." (PMID 42074079, 2026). "The up‐regulated genes in tumor‐infiltrating myeloid cells in RARα‐KO mice included Rnf128, Cd36, Nos2, Prdx1, Cd274, and H2‐Q4, associated with the immune‐activating phenotype." (PMID 40068101, 2025). "Together, these results indicate that MSL1 modulates tumor immunity by influencing CD274 expression and its associated signaling networks." (PMID 41409271, 2025). "IRF1 has been shown to upregulate CD274 (that encodes PD-L1) expression in the tumor microenvironment and IRF1 “knock-out” has been shown to render tumor cells more susceptible to CD8+ T cell-mediated killing." (PMID 40428397, 2025). "Significant transcriptomics changes in tumor biopsies from pre-treatment to 2 weeks after axi-cel with the upregulation of immune checkpoint encoding genes (CD274, CD276, and CTLA-4) were also associated with response to therapy." (PMID 39858099, 2025). "Overall, the top four checkpoint genes associated with KLF4 and correlated with a tumor inhibitory effect in several tumors were C10orf54, CD274, IL10, and TGFB1." (PMID 40299916, 2025). "PSD3 appears to skew the tumor milieu toward immune suppression, while CD274 is linked to both stimulatory and suppressive immune components." (PMID 40895529, 2025). "These are Ccl4+Cd274+Lcn2+Ptgs2+ immunosuppressive neutrophils implicated in EMT induction in tumor cells." (PMID 40568084, 2025). "MALT1 protected CD274 mRNA from degradation and promoted the proliferation and polarization of tumor-associated macrophages to create an immunosuppressive tumor microenvironment." (PMID 40725006, 2025). "Cd274 (encoding PD-L1), Cd47, and Sirpa, all implicated in tumor immune escape, were also all significantly upregulated." (PMID 41445746, 2025). "First, we tested associations of endogenous IGF1 expression with CD274 (PD-L1 mRNA), finding significantly higher CD274 in tumours with the highest (n = 124) quartiles of IGF1 when compared with the lowest (n = 125)." (PMID 41184420, 2025). "Our findings indicated that patients with LRP1B mutations exhibited higher expression levels of CD274, increased abundance of tumor‐infiltrating lymphocytes, elevated TMB, and improved survival outcomes." (PMID 39660409, 2024). "Correlation analysis was performed between the expression of circAATF and the CD274 gene (encoding the PD‐L1 protein) in GBC tumour samples." (PMID 39428382, 2024). "Another work focusing on interaction between astrocytes and microglia demonstrated that tumor-associated astrocytes (TAAs) express high levels of CD274 (PDL-1), CHI3L1, and STAT3, which are associated with alternatively activated astrocytes." (PMID 38786032, 2024). "This is due to the fact that immune checkpoint genes, such as CD274, cause T cell dysfunction, hindering the ability of cytotoxic T cells to target tumor cells." (PMID 38517387, 2024). "Combined with TCGA and CGGA cohort, TRIM56 was most closely correlated with LAIR1, CD44, PDCD1LG2 and CD274, and oncoplots were used to display the tumor mutation gene microlandscape of TRIM56 high expression group and low expression group." (PMID 38348047, 2024). "In order to shed light on this question, a 4-gene inflammatory signature comprised of CD8A, STAT1, LAG3, and CD274 (encoding PD-L1) was assessed by the RNA-sequencing of the baseline tumor samples of patients included in the CheckMate-816 study." (PMID 39123401, 2024). "For example, CD274 (PD-L1) encodes an immune inhibitory receptor ligand, and its expression is associated with tumor immune escape in many types of cancers." (PMID 38566223, 2024). "LUAD subtypes were able to predict immunotherapy response in addition to CD274 (PD‐L1) gene expression and tumor mutational burden (TMB)." (PMID 37943164, 2024).
tumor (continued). "PDCD1 is mainly expressed by CD4+ and CD8+ T lymphocytes, whereas its ligand, CD274, is widely expressed in various cell types including activated lymphocytes, fibroblasts, tumor-associated macrophages and tumor cells." (PMID 36979400, 2023). "Activated T cells express PD-1 encoded by the PDCD1 gene, while PD-L1 encoded by the CD274 gene is overexpressed on the membrane surface of tumor cells." (PMID 37980541, 2023). "Our observations showed that CD70 and CD274 are co-associated with IFNγ expression and are predominantly expressed in different immune cell types within the tumor microenvironment." (PMID 37106127, 2023). "Tumor-induced erythroid cells had a high expression of CD274 and other genes encoding immune checkpoints, Fam132b (also known as Erfe, or encoding erythroferrone), and Osm (encoding oncostatin M)." (PMID 37894821, 2023). "Programmed death-ligand 1 (PD-L1), encoded by the CD274 gene, is a receptor expressed by tumor cells and their associated stromal cells." (PMID 37056391, 2023). "The FACS analysis of immune cell profiles showed that the expression of USP12 was negatively correlated with tumor-associated macrophages (TAMs) and PD-L1 (CD274), which were significant for tumor immune therapies." (PMID 37752518, 2023). "Blockade caused by anti-CD274 mAb binding restores Teff cell activation and enhances cytotoxic immune response against tumor cells." (PMID 37215135, 2023). "Previous studies showed that SNV in the 3' UTR region of CD274 gene is related to the binding of microRNAs and cause PD-L1 overexpression, which contributes to tumor cell immune escape." (PMID 36717553, 2023). "Programmed death 1 (PD-1) ligand (PD-L1) (CD274) expression, tumor mutation burden (TMB), and microsatellite instability (MSI) status of tumor tissue are potential predictors of anti-PD-1 treatment response." (PMID 36875764, 2023). "PD-L1, which is a protein encoded by the CD274 gene, is overexpressed by numerous tumor cells as a strategy to evade immune responses." (PMID 36923449, 2023). "Previous studies on molecular mechanisms have revealed that mutations in the UTR region of CD274 gene can instigate the immune escape of tumor cells by inhibiting the microRNA suppressive regulation of PD-L1 expression." (PMID 36717553, 2023). "In hypoxic tumor cells, the central hypoxia-inducible factor HIF-1α transactivates CD274, the gene encoding PD-L1 protein, and leads to tumor immune escape from CD8+ cytotoxic T cells." (PMID 36747292, 2023). "Studies have also shown that the expression of PD‐L1 protein (encoded by the CD274 gene) in tumor cells has been proposed as a predictive biomarker of response to anti‐PD‐1/PD‐L1 treatment." (PMID 35229456, 2022). "Plenty of evidence have shown that PD-L1 (encoded by CD274) serves critical roles during tumor immune escape as well as tumor invasion and progression, and was proved to be valuable biomarker to predict worse prognosis for human cancers." (PMID 36276934, 2022). "Deletion of CD274 (which encodes PD-L1) in T cells enhances adaptive tumour immunity and activates TAMs, indicating that the use of anti-PD-1/PD-L1 inhibitors will enhance immunity in tumours with a high density of CD4+FoxP3−PD-L1+ T cells." (PMID 35982052, 2022). "It has been proved that several mechanisms encoded by CD274 can regulate the expression of PD-L1 16, intracellular factors, and tumor microenvironment." (PMID 36313041, 2022). "PD-L1, encoded by the CD274 gene, is mainly expressed on the cell membrane surface of tumor cells and some immune cells including macrophages and dendritic cells(DCs)." (PMID 35958549, 2022). "They found that miR-155 overexpression increased CD274 (programmed death ligand 1 [PD-L1]) expression on cancer cells and tumor-associated macrophages." (PMID 36189796, 2022). "Studies have ascertained that PDCD1 and CD274 expressions in tumor cells and tumor-infiltrating immune cells are associated with improved prognosis, which supports our finding." (PMID 35356506, 2022).
tumor (continued). "Tumor mutation burden (TMB) had weak positive correlations only with CD274 (p = 0.01342; R = 0.127), CXCL9 (p = 0.038; R = 0.1078), and also with the XP cluster 2 genes ERCC3 (p = 0.00196; R = 0.157) and ERCC2 (p = 0.027; R = 0.114)." (PMID 35174087, 2022). "Previously, IRF1 has been implicated not only in the regulation of CD274 (PD-L1) expression, but also in playing a role in suppressing tumour proliferation and stimulating an active immune response in tumours." (PMID 36010935, 2022). "Programmed death ligand 1 (PD-L1, also named B7-H1 or CD274), which is overexpressed on tumor cells and tumor-associated macrophages (TAMs), binds to PD-1." (PMID 36213322, 2022). "Three widely used biomarkers related to ICI therapy response; microsatellite instability (MSI), CD274 expression, and tumor mutation burden (TMB), were tested in two risk groups in the TCGA cohort." (PMID 36313898, 2022). "Our immune marker analysis also found CD274 (PD-L1) expression, strongly associated with tumor macrophages, to be elevated in later-onset SARC." (PMID 34788626, 2021). "In contrast, there were significantly lower values in the high-risk group regarding interferon-gamma (IFNG), MSI score, Merck18, CD274, and tumor-associated macrophage M2 (Mann–Whitney U test P < 0.001)." (PMID 34541005, 2021). "The CD274 gene encodes the protein, Programmed Cell Death 1 Ligand 1 (PD-L1), which inactivates cytotoxic T-cells and helps tumor cells escape from immune damage by cytotoxic T-cells." (PMID 34439934, 2021). "The genotype profile of 97 single-nucleotide polymorphisms (SNPs) from 19 ICK-related genes was analyzed in an extended cohort of PC patients (n = 1762); the CD274 gene (encoding for PD-L1) was correlated with biochemical recurrence and tumor progression." (PMID 34945784, 2021). "Regrettably, the low tumor mutation burden and the rare CD274 (PD-L1) amplifications observed in PSCC hint at low responsiveness to immunotherapy." (PMID 35008677, 2021). "Recent meta-analyses of the efficacy of antibodies targeting PDCD1/CD274 as monotherapy found that this treatment is associated with more tumor responses and increased overall survival (OS) compared to conventional therapy." (PMID 34067485, 2021). "As a ligand for PD-1, PD-L1 is a transmembrane protein expressed on immune cells and tumor cells encoded by the CD274 gene." (PMID 34539884, 2021). "Induction or oncogeneic activation of PD-L1 in non ‘inflamed’ tumours occurs through alternative pathways such as loss of PTEN or copy gain / amplification of CD274/PDL1 locus (Ch 9p24.1)." (PMID 32294103, 2020). "Previous studies have demonstrated a significant association between EMT and expression of PD-L1 (CD274), one of the key molecules that block anti-tumor immune response, in HNSCC." (PMID 33142242, 2020). "Most of the stimulated genes benefit to antitumor immunity, while others like CD274 (encoding PDL1) lead to inactivation of tumor-specific T cells." (PMID 32793604, 2020). "Tumor-associated PD-L1 (CD274) can block tumor-specific T cell-mediated immunity by inducing apoptosis of T cells, suppressing the secretion of cytokines and disturbing the function of activated T cells." (PMID 32373519, 2020). "Remarkably, we found a significant association between the IRE1α gene signature and CD274 gene expression in tumor-infiltrating macrophages in humans." (PMID 32520957, 2020). "Programmed death-ligand 1 (PD-L1), encoded by CD274 gene, is an immune inhibitory ligand that is expressed on various tumor cells." (PMID 32275681, 2020). "Expression of PD-L1 (encoded by CD274) has been shown to be regulated, in part, by DNA methylation and as such is up-regulated in tumor cells by DNMTIs." (PMID 31911474, 2020). "We previously showed that programmed death-ligand 1 (PD-L1) also known as CD274 on tumor cells is associated with reduced MHC I (APM) expression in HGSOC." (PMID 30131693, 2018).
tumor (continued). "In conclusion our result showed that PD‐L1 (CD274) expression in tumor cells is associated with chemoresistance and the poor prognosis of HNSCC through IL‐6." (PMID 29761938, 2018). "CD 274(PD-L1) proportion was confirmed as independent associated factors of total regression when age, gender, location of tumor, pretreatment CEA, clinical T stage were adjusted." (PMID 29108360, 2017). "CD274 encodes an immune inhibitory receptor expressed on T cells, B cells and various tumor cell types." (PMID 29135455, 2017). "Separately, genetic rearrangements in the 3′ UTR of CD274 (encoding PD-L1) have been found in a multitude of different cancers at low frequency and are associated with massively increased expression of tumor PD-L1." (PMID 29246442, 2017). "Of these genes, we validated CD274, which encodes PD-L1, an immune tolerance-regulatory molecule from tumor cells." (PMID 28851898, 2017). "In ovarian cancer, alterations of homologous repair genes including BRCA1 have been associated with CD274 expression and tumor-infiltrating lymphocytes." (PMID 27683114, 2016). "Additionally, the C allele of rs4143815 in CD274 was associated with PD-L1 positivity in tumor cells (p = 0.039)." (PMID 42074079, 2026). "To investigate whether IFNγ directly acts on tumor endothelial cells, we analyzed the expression of programmed death ligand 1 (PD-L1) as a readout of IFNγ signaling (Cd274 encoding PD-L1 is an IFNγ-stimulated gene)." (PMID 40460830, 2025). "These include NT5E (CD73) and ENTPD1 (CD39) which are involved in immunosuppressive adenosine signaling, LGALS1 (galectin-1) and TGFB1, which encode for anti-inflammatory cytokines, and CD274 (PD-L1), which binds to PD-1 to initiate an inhibitory signaling pathway in anti-tumor immune cells." (PMID 40277917, 2025). "However, some genes, such as CD274 (encoding PD-L1), have the opposite effect of inactivating tumor-specific T cells." (PMID 40075727, 2025). "In particular, the high expression of CD274 (PD-L1) may inhibit T cell function, promote tumor cell immune escape, and lead to poor prognosis in high-risk group patients." (PMID 41003841, 2025). "Indeed, Cd274 (encoding PD-L1) was ~125-fold increased, on tumor cells (CD45DEPR TU cell fraction) compared with the immune cell fraction (represented by both the CD11bEN and CD45EN TU cells)." (PMID 40842154, 2025). "Following this, we delved into whether miR-4429 could influence the PI3K/AKT signalling pathway, a pathway intricately linked with CD274 and tumour development." (PMID 38802631, 2024). "Thus, both CHL-IDD and de novo CHL tumor cells exhibit heterogeneity in the genomic aberration of the 9p24.1 region containing the CD274 gene that encodes PD-L1 within the tumor." (PMID 38610976, 2024). "Furthermore, the creation of β-catenin/LEF/TCF complex to the CD274 promoter region caused by the accumulation of β-catenin stimulates the PD-L1 expression, further promoting tumor immune evasion and weakening the impact of PD-1/PD-L1 inhibitors." (PMID 38424042, 2024). "PD-L1 (encoded by CD274) is a transmembrane protein synthesized in the endoplasmic reticulum of tumor cells and its interaction with the programmed cell death protein 1 on T-cells restrains antitumor immunity by T-cell activation inhibition or apoptosis, thus leading to cancer’s immune evasion." (PMID 38257813, 2024). "Mutations in genes, such as CD274 (encoding PD-L1), help tumor cells evade the immune response." (PMID 37958472, 2023). "Furthermore, Cyp11b1‐deficient tumours had reduced expression of the immunoregulatory molecules CD274 (PD‐L1), CD152 (CTLA‐4) and IL‐10." (PMID 36861295, 2023). "These differential mechanistic links may underlie the observed inverse association of tumor CD274 upregulation and F. nucleatum abundance." (PMID 37538192, 2023). "This may also explain why patients in the high-risk group have a worse prognosis, as immune checkpoint genes, such as CD274, are associated with tumor cells that evade immune surveillance." (PMID 38071230, 2023).
tumor (continued). "In previous studies, it remains controversial whether blood-based CD274 assay results can reflect mutations or PD-L1 expression difference in-situ tumor tissue due to blood CTC-based PD-L1 assay relies on ELISA and qPCR techniques." (PMID 36717553, 2023). "Notably, the squamous variant exhibited a substantial presence of CD-274 gene amplification (5%), PD-L1 expression, and a high tumor mutational burden (TMB), all of which suggest its potential responsiveness to ICI treatment." (PMID 37715113, 2023). "cSMART 2.0 was used to detect rare variants in the UTR region of CD274 gene in multi-omics methodology for the first time in a large-scale retrospective cohort covered a variety of tumor types, while correlating their presence with the efficacy of immunotherapy." (PMID 36717553, 2023). "Using the two‐sided α level of 0.005, F. nucleatum abundance was significantly associated with poor tumor differentiation, CpG island methylator phenotype (CIMP)‐high status and microsatellite instability (MSI)‐high status, whereas tumor CD274 overexpression was associated with non‐MSI‐high status." (PMID 37538192, 2023). "In our primary hypothesis testing, we conducted an ordinal logistic regression analysis to assess the association of tumor CD274 expression with the amount of tumor F. nucleatum DNA." (PMID 37538192, 2023). "CD274, also known as PD-L1, has been implicated in inducing immune evasion by tumor cells." (PMID 37716991, 2023). "Third, the molecular mechanism of expression changes caused by SV in the UTR region of the CD274 gene, which leads to immune escape of tumor cells and may serve as a biomarker of ICI efficacy, requires further molecular cell biology experiments to confirm." (PMID 36717553, 2023). "In addition, expression of Cd274 gene (known as PDL1), closely linked to tumor immune evasion, was downregulated in Nlrp3-/- G-MDSCs." (PMID 36032139, 2022). "To further explore the significance of our model with respect to the tumor microenvironment, we analyzed the differences in the expression of CD274/PD-L1 as well as the infiltration of CAFs and tumor-associated macrophages (TAMs) in high-risk and low-risk patient groups." (PMID 35585970, 2022). "Higher objective response rates to PDCD1/CD274 monotherapy have been associated with a number of factors, including immunogenicity of the tumor, male sex, age < 65 years, current and former smokers, a lack of central nervous system or liver metastasis, and a lack of EGFR mutations." (PMID 34067485, 2021). "Analysis of expression of CD274 (PD-L1) and PDCD1LG2 (PD-L2) is shown with respect to stage - there was a significant increase in PD-L1 (CD274) expression associated with increased tumor stage (pT1-T2+ p=0.0031, pTa-T2+ p=<0.0001; one-way ANOVA with Tukey’s multiple comparison)." (PMID 33718196, 2021). "The relationship between ICGs positively correlated with CD274 and immunotherapy biomarkers (tumor mutation burden (TMB), and adaptive immune resistance pathway genes) was investigated, and the relationships of these genes with OSCC clinical features were explored." (PMID 35127742, 2021). "Several different tumor types express PD-L1 either due to up-regulation after mutations in the PD-L1 gene (CD274) or as a result of adaptive up-regulation after stimulation with inflammatory cytokines (i.e., interferon-gamma (IFNγ)) present in the microenvironment." (PMID 32325898, 2020). "A positive response to checkpoint inhibitor therapy has been associated with a high expression of PD-L1/CD274 on tumor-infiltrating immune cells indicating a role for PD-L1/CD274-expressing immune cells in suppressing antitumor responses, which are reinvigorated on checkpoint blockade therapy." (PMID 33066260, 2020). "Specifically, tumor cells expressed PD-L1 (encoded by CD274) and PVR transcripts, which could transmit inhibitory signals to PD-1 (encoded by PDCD1 gene) and TIGIT on T cells, respectively." (PMID 32460812, 2020).